CCL2 (C-C motif chemokine ligand 2)
Diseases named in the same sentence as CCL2 in open-access papers (continued):
Sharing a sentence is not in itself a finding about the gene and the disease.
tumor (continued). "Macrophages are known to produce CCL2 in response to IL-4/IL-13 stimulation, and the increase in CCL2 production we detected during lung tumorigenesis indicates that there is a Th2 response occurring in lungs during tumor formation." (PMID 25505466, 2014). "Three CC chemokines, CCL2, CCL11, and CCL16, have also been implicated in tumor neovascularization." (PMID 24966464, 2014). "Indeed, the pharmacological inhibition of CCL2 with Bindarit reduced macrophage recruitment and suppressed tumor growth." (PMID 25125485, 2014). "TAMs are initially mobilized from the bone marrow and recruited to the tumor site by specific tumor-derived stimuli and inflammatory CC chemokines (e.g., CCL2), while their recruitment and survival are sustained by cytokines present in the tumor microenvironment (e.g., CSF and VEGF-A)." (PMID 24578639, 2014). "Tumour infiltrating macrophages, also indicated as TAMs, derive from circulating monocytic precursors and are recruited to tumour sites by several molecules, such as the chemokines CCL2 and CCL5, VEGF, TGF-β, and colony stimulating factors (GM-CSF and M-CSF)." (PMID 24741617, 2014). "Extracellular ATP released from neuroblastoma cells may act in paracrine/autocrine model driving tumor proliferation and, at the same time, activating myeloid-derived immunosuppressive cells that produce growth-promoting chemokines like CCL2." (PMID 25530618, 2014). "Monocytes are actively attracted to the tumor site and differentiate into TAMs as a result of the production of cytokines and chemokines by tumor cells, such as monocyte chemoattractant protein-1 [or chemokine CC ligand (CCL2)], RANTES (or CCL5) and vascular endothelial growth factor." (PMID 25280428, 2014). "CCL2 is expressed by many tumor types as well as by the peripheral myeloid population." (PMID 25054153, 2014). "CC chemokine ligand 2 (CCL2) is a major chemoattractant for tumor-associated monocytes; however, TEMs do not express the receptor CCR2 on their surface." (PMID 24809734, 2014). "Several chemokines, particularly CCL2, can induce tumor angiogenesis by attracting TAMs and MDSCs." (PMID 24966464, 2014). "Furthermore, MDSC expansion and MDSC-mediated liver injury further increased with growing tumor burden and was associated with different cytokines including GM-CSF, VEGF, interleukin-6, CCL2 and KC, depending on the tumor model used." (PMID 25401795, 2014). "Presently, only few studies have investigated the role of CCL2 in tumor angiogenesis." (PMID 24971349, 2014). "Moreover, in a mouse liver metastasis model, tumor-derived CCL2 was found to induce α-SMA-positive HSCs to accumulate at tumor sites and to express MMP-2." (PMID 24966464, 2014). "Thus, our results suggest that combined blockade of prostate AR and anti-CCL2/CCR2 signalling reduced primary tumour growth and distant metastases (siAR veh vs. siAR CCR2atg, p = 0.003)." (PMID 23982944, 2013). "Pleural tumor microvessel density was not different between IgG2a- and anti-CCL2/12 combination-treated mice with LLC- or MC38-caused MPEs; however, blood vessels in CCL2/12-targeted mice appeared smaller and less organized." (PMID 23967166, 2013). "It was possible that the decreased serum level of CCL2 may reflect increased local consumption in tumor." (PMID 23697837, 2013). "TAMs originate from circulating monocytic precursors, which are recruited within the tumor microenvironment by tumor-derived signals, including Chemokine (C-C motif) Ligand 2 (CCL2) and Macrophage Colony-Stimulating Factor (M-CSF), and differentiate into mature macrophages." (PMID 23533994, 2013). "Second, CCL2 may promote metastatic tumor growth only in tumors and models where the chemokine facilitates metastatic homing, i.e., a chance for tumor cells to grow." (PMID 23967166, 2013). "Third, CCL2 may selectively promote tumor growth in models that require CCL2-mediated immune evasion, in contrast to MPE where CCL2 apparently functions as an escalator of frank inflammation." (PMID 23967166, 2013).
tumor (continued). "Similarly, Bindarit® that inhibits CCL2 synthesis and therefore restricts the recruitment in the tumor of immature myeloid cells, was shown to induce tumor regression in prostate and breast cancer animal models." (PMID 23763830, 2013). "The same group has discovered that MYCN non-amplified high risk NB tumors produce the chemokine CCL2 which attracts invariant (i) NKT cells to the tumor site." (PMID 23805414, 2013). "The tumor microenvironment promotes the generation of type 2 macrophages, as tumor cells can secrete factors (such as CCL-2) that recruit macrophages to the site of the tumor, and once there the immunosuppressive tumor microenvironment is able to drive these macrophage toward a type 2 phenotype." (PMID 23653893, 2013). "Importantly, combined targeting of PCa AR (with AR-siRNA) and anti-CCL2/CCR2 axis (with CCR2atg) notably suppressed the growth of orthotopic TRAMP-C1 tumours (siAR veh vs. siAR CCR2atg, p = 0.018)." (PMID 23982944, 2013). "Therefore targeting CCL2 signaling in regulation of tumor progression in bone metastases is an area of intense research." (PMID 23698775, 2013). "For example, since radiation therapy is known to induce hypoxia in tumor beds, blocking VEGF or CCL2 could potentially stop the recruitment of macrophages to these hypoxic tumor areas and slow or stop tumor progression." (PMID 23673510, 2013). "In addition to tumor-promoting effects, CCL2 signaling is involved in regulation of the tumor microenvironment, playing a role in osteoclast and macrophage biology as well as angiogenesis." (PMID 23698775, 2013). "Our PCa mouse model clearly demonstrated that increased CCL2 and EMT markers in AR silenced PCa cells were associated with increased distant metastasis, in spite of reduced size of orthotopic AR silenced primary tumours." (PMID 23982944, 2013). "In addition to its angiogenic function, CCL2 acts as a chemoattractant molecule that recruits not only tumor cells, but also leukocytes that provide growth factors for the immigrant population of tumor cells." (PMID 24399973, 2013). "Moreover, WT mice receiving the tumor expressing 7ND exhibited reduced serum mouse CCL2 concentration compared with WT mice receiving parental Col26 cells." (PMID 22815949, 2012). "We have recently shown that CCL2 is predominantly expressed at the human primary tumor site of patients suffering from CaP, which leads to selective breakdown of immunological tolerance resulting in a production of anti-CCL2 autoantibodies that are likely to participate in the regulation of disease." (PMID 22279523, 2012). "Furthermore, CCR2 expression by thymic Sirpα+ cDCs and abundant expression of its ligands, particularly, CCL2 by tumor-bearing mice prompted us to examine the function of thymic Sirpα+ cDCs in tumor-bearing mice." (PMID 22815949, 2012). "Given the abundance of proteoglycans in the IVRs in the thymus, serum CCL2 might be deposited inside the IVRs through binding with proteoglycan after tumor development." (PMID 22815949, 2012). "Thus, besides the recent reports showing the tumour cytotoxicity of N1 TANs through TGF-β blockade and tumour-entrained neutrophils by CCL2, we identify a new mechanism mediated by IL-1β." (PMID 23065753, 2012). "Importantly, all the cases studied showed CCL2 immunoreactive cells, while the shape of the areas of immunoreactivity differed according to the structure of the tumor." (PMID 22319587, 2012). "We next addressed whether production of the proinflammatory cytokine was under the control of the MAPK pathway by testing the effect of the inhibitors on Ccl2 gene expression and cytokine production by the Amela tumor cells." (PMID 23173060, 2012). "In such a setting, inflammatory cells that were recruited to the tumor site in response to chemokines such as CCL2 and CCL5 continue releasing the inflammatory cytokines TNFα and IL-1β, whose activities further promote the release of the cancer-related chemokines." (PMID 24213226, 2012).
tumor (continued). "We have indication that IL-6 and CCL-2 levels are increased in our OTC tumor model." (PMID 22792213, 2012). "Importantly, confocal co-localization analysis revealed that astrocytes were the CCL2-expressing cells in the tumor area." (PMID 22319587, 2012). "Gene therapy of tumor cells with CCL2 or CCL2/anti-tumor Ab fusion proteins may attract CTLs that potentially could inhibit tumor growth." (PMID 21450101, 2011). "Our study demonstrates the role of CCR2 and CCL2 in migration of CTLs towards tumor." (PMID 21450101, 2011). "Furthermore, these results suggest that in this specific sub-group of IDC-with-relapse patients, the two cytokines are coordinated with other tumor-supporting factors that replace CCL2 & CCL5 in promoting disease relapse." (PMID 21486440, 2011). "However, tumor cells secreting low amounts of CCL2 promote tumor growth by stimulating angiogenesis." (PMID 21450101, 2011). "Although CTL007 has several chemokine receptors matching chemokine produced by CRC cells, predominant expression of CCR2 (65%) by the T cells and the relatively higher amount of CCL2 secretion by tumor cells may have been a decisive factor in T-cell migration." (PMID 21450101, 2011). "Also, the secretion of CCL2 by tumor cells results in infiltration of tumor cells by leukocytes including T cells, NKT cells and macrophages." (PMID 21450101, 2011). "CCL2 secretion by tumor cells can aid in tumor progression, angiogenesis and metastasis." (PMID 21450101, 2011). "In addition, three CC chemokines, CCL2, CCL11, and CCL16 have also been implicated in tumor neovascularization." (PMID 24212934, 2011). "We examined if specific individual components of the tumour conditioned media (CCL2, CXCL1, CXCL5) could modulate dendritic cell maturation or cytokine secretion in response to LPS." (PMID 22125641, 2011). "Studies have shown that this drug causes a decrease in the normal cells’ production of the proinflammatory chemokine (C-C motif) ligand 2 (CCL2), which recruits monocytes to the tumor sites, and a decrease of interleukin-6 (a growth factor implicated in several malignancies), and VEGF." (PMID 22113577, 2011). "Blocking CCL-2 reduced the number of tumor-infiltrating macrophages in pre-clinical animal studies." (PMID 22176642, 2011). "The chemokine CCL2 is produced by BMECs and stimulates Rac1-mediated tumor cell diapedesis." (PMID 21776386, 2011). "Under such conditions, TNFα & IL-1β would not act on the tumor cells to promote the release of CCL2 & CCL5, leading to lack of associations between the two cytokines and CCL2 & CCL5." (PMID 21486440, 2011). "Furthermore, recent findings obtained in our studies suggest that TNFα and IL-1β exert tumor-promoting activities that are connected to the ability of CCL2 and CCL5 to function as cancer-supporting factors." (PMID 21486440, 2011). "On the other hand, CCL2 blockade inhibited tumor growth and metastasis in lung cancer mouse models." (PMID 21826248, 2011). "Here we find that RhoG partially contributes to CCL2-induced tumor cell diapedesis." (PMID 21776386, 2011). "Identification of tumor cells secreting CCL2 or T-cells expressing CCR2 in the tumor microenvironment could be a useful prognostic marker in CRC patients." (PMID 21450101, 2011). "We have shown that the chemokine CCL2 induces tumor cell diapedesis via Rac1 activation." (PMID 21776386, 2011). "We propose that CCL2 may affect two aspects of tumor development by enhancing the pro-apoptotic function of rVP1 and by contributing to the absence of intra-hepatic metastasis (between lobes) in rVP1-treated mice." (PMID 21826248, 2011). "Therefore, mast cells probably promote the migration and suppressor function of tumor MDSCs by regulating the expressions of CCL2 and Th2 cytokines." (PMID 20111717, 2010). "On the basis of these findings, we propose that CCL2/CCR2 axis may be an important signaling pathway for MDSC recruitment to tumor microenvironment." (PMID 20111717, 2010).
tumor (continued). "NBEC expressed IL-12R and released constitutively tumor promoting cytokines (e.g. IL-6 and CCL2)." (PMID 19582164, 2009). "Of the informative tumours that did not express CCL2 by Northern blot, six had LOH and one had no loss, while one tumour that did express CCL2 also had LOH." (PMID 15900302, 2005). "Similarly, the CC chemokine ligand 2 CCL2/MCP-1 (MCP=monocyte chemoattractant protein 1) has been identified as a major chemokine for macrophages recruitment in several human tumours, including the bladder, cervix, ovary, lung and breast." (PMID 15164120, 2004). "However, in certain contexts, CCL2 and GM-CSF can also promote anti-tumor immune responses." (PMID 41513619, 2026). "CCL2 influences the recruitment of various immune cells, including invariant natural killer T (iNKT) cells, dendritic cells (DCs), monocytes, macrophages, and regulatory T cells (Tregs), thereby shaping either pro- or anti-tumor responses depending on the context." (PMID 41936749, 2026). "Additionally, CCL2 may promote macrophages for epithelial-to-mesenchymal transition, making the tumor more prone to metastasis." (PMID 39996747, 2025). "Chemokines such as CCL2, CCL18, and CXCL12 are instrumental in promoting either a pro-inflammatory M1 phenotype, which is associated with pathogen clearance and tissue damage, or an anti-inflammatory M2 phenotype, which is involved in tissue repair, fibrosis, and tumor progression." (PMID 40330466, 2025). "Macrophages also migrate to the tumor site, where tumor cells are responsible for a switch in macrophage phenotype, favoring a pro-invasive and immunosuppressive M2 state via the release of immunosuppressive factors, such as CSF-1, CCL2, IL-4, IL-6, IL-10, and TGF-β." (PMID 41373591, 2025). "The elevation of CCL2 levels along the superficial-to-deep layer axis indicated the presence of immunosuppressive immune cell subtypes that may contribute to tumor cell aggressiveness in the deep invasive layer of diffuse-type GC, and CCL2 expression correlated with poor survival in GC." (PMID 40075643, 2025). "At the same time, Rg3 inhibited STAT3 activation, reduced tumor cell secretion of CCL2, reduced the recruitment of MDSCs and TAMs in the lungs, destroyed the metastatic microenvironment, inhibited tumor cell growth and metastasis, increased tumor cell apoptosis, and reduced tumor size." (PMID 40292112, 2025). "Interestingly, Treg cells might be recruited to the TME by cytokines such as CCL2 and CCL17 produced by tumor-associated neutrophils, thus promoting the progression of HCC and resistance to Sora." (PMID 39743020, 2025). "Therefore, metastatic tumor cells in several types of cancer may promote tumor progression by activating CCL2-related signaling pathways and subsequent CCL2 secretion." (PMID 40343498, 2025). "The TME plays a pivotal role in carcinogenesis by maintaining a balance between tumor-suppressing cytotoxic cells and tumor-supporting cells like M2 macrophages and myeloid-derived suppressor cells (MDSCs), which are recruited by inflammatory cytokines such as CCL2." (PMID 40647432, 2025). "Additionally, GEM treatment (20 mg/kg) stimulates the production of CCL2 in the tumor cells which recruits M-MDSC to the tumor niche, and CCL2 receptor antagonists, such as RS 504393, could block M-MDSC recruitment." (PMID 40270972, 2025). "Our primary aim of this study is to elucidate the potential involvement of KCa3.1 and LRRC8A in regulating CCL2 expression and production through these signaling axes in M2-MACs, as well as their role in CCL2 upregulation under high-[K+]e conditions that mimic the tumor microenvironment." (PMID 40806751, 2025). "Similarly, the chemokine receptor CCR2 expressed by MDSCs and the chemokine CCL2 produced by tumour cells play a pivotal role in mediating the recruitment of MDSCs into tumours; in brief, iNOS in MDSCs hampers T-cell migration through its impact on the chemokine CCL2." (PMID 40429821, 2025).
tumor (continued). "Moreover, a CCL2 blockade has been shown to shift TAMs toward anti-tumor M1-like phenotype." (PMID 39857957, 2025). "Besides, cytokines such as CCL2 and IL‐8 facilitate the recruitment and tumor infiltration of MDSCs, which facilitates senescence of immune cells by both the manner of direct cell‐cell interactions (via PD‐L1/PD‐1 axis) or long‐range communication (through exosomes or soluble factors like TGF‐β)." (PMID 41427020, 2025). "CCL2 may also modulate monocyte–macrophage crosstalk within the tumor niche." (PMID 40909271, 2025). "Thus, MakA-driven CCL2 expression may represent a mechanism for reprogramming macrophage responses toward tumor inhibition." (PMID 41326332, 2025). "Therefore, we hypothesize that once microglia adopt the M2-polarized phenotype, IL6 and CCL2 in the tumor microenvironment are mainly secreted from microglia." (PMID 40444044, 2025). "Additionally, CCL2 overexpression enhances cancer cell migration and recruits immunosuppressive cells to the tumor microenvironment, creating conditions that support tumor progression, and its elevated expression is associated with a poor prognosis in GBM patients." (PMID 40149846, 2025). "In addition, a previous report indicated that reactive nitric species could modify the chemokines such as CCL2, inhibiting the induction of anti‐tumor lymphocytes." (PMID 39947253, 2025). "Finally, we explored whether the elevated CCL2 contribute to the tumor-promoting effects mediated by M2a macrophages induced by CC-derived exosomal CMTM6." (PMID 40761779, 2025). "Moreover, these extracellular vesicles can also participate in chemotactic signaling, actively recruiting MDSCs or TAMs into the tumor niche by transporting chemokines such as CCL2 and CXCL12, further contributing to the establishment of a protumoral microenvironment." (PMID 40630800, 2025). "Similarly, analysis of pro-inflammatory tumor microenvironment markers demonstrated elevated expression of IL-8 (P<0.0001 and P=0.0003), CCL2 (P=0.0139 and P=0.0007), and COX2 (P=0.0274 and P=0.0013) in the right colon of PSC patients compared with both IBD alone and control groups." (PMID 40476597, 2025). "Given the multiple reports that have classified CCL2 expression as having a role in the accumulation of CCR2+ TAMs in the PDAC TME, which has been associated with a decreased prognosis, trials have been initiated to understand if blocking CCR2 enhances anti-tumor effects in PDAC." (PMID 38339310, 2024). "Consequently, blocking CCL2 can alleviate tumor progression." (PMID 39456702, 2024). "Tumoral CCL2 knockdown could have upregulated cytokines that promote immune infiltration." (PMID 38973385, 2024). "In breast cancer, obesity causes the CCL2 signal to initiate chronic inflammation, thus leading to the recruitment to the TME of many macrophages and fibroblasts, thus resulting in collagen deposition and tumor fibrosis in the TME and significantly promoting tumor progression." (PMID 38787372, 2024). "TPV/∆66R/m-IL-2/mCherry and TPV/∆66R/m-CCL-2/mCherry virotherapy in immune-reconstituted animals demonstrated similar trends over the course of the study, with the results from both recombinants showing less overall regression in tumor volume compared to control." (PMID 39200298, 2024). "Moreover, CCL2 knockdown could have altered production of cytokines from tumor tissues that systemically affect muscle tissue." (PMID 38973385, 2024). "Additionally, macrophage secretion of EGF induced by CCL2 promotes ESCC tumor growth." (PMID 39596630, 2024). "The differences in the immune system could have affected tumor growth with CCL2 knockdown." (PMID 38973385, 2024). "Therefore, the MSCs-CCL2-monocyte axis has significant physiological significance in tumor progression, and the blockage of this interaction may be an effective strategy for targeted cancer treatment based on MSCs." (PMID 38779660, 2024).